DDX54 (DEAD-box helicase 54)
Description:
Nucleolar RNA helicase that is involved in diverse cellular processes including ribosome biogenesis, DNA damage response, RNA splicing, transcriptional regulation, innate immunity, and nervous system development. Plays an essential role in the formation of the ribosome active site by remodeling rRNA structure and initiating peptidyl transferase center formation. Represses the transcriptional activity of several nuclear receptors. Regulates transcriptome dynamics during DNA damage response. Mechanistically, acts via increased interaction with a well-defined class of pre-mRNAs that contain introns with weak acceptor splice sites, as well as by protein-protein contacts within components of U2 snRNP and spliceosomal B complex. These activities lead to reduced intron retention and enhanced processing rates of its target transcripts. Acts as an inhibitor of type I interferon antiviral response by facilitating ALKBH5-mediated demethylation of specific transcripts. Contributes to central nervous system myelination, likely through regulation of oligodendrocyte differentiation and myelin sheath formation (By similarity).
Synonyms: MGC2835; APR-5; DP97
Tractability: Small molecule: a structure with a bound ligand is known. PROTAC: ubiquitination databases record sites on it; its protein half-life has been measured.
Gene: Protein-coding gene on chromosome 12 (113,157,173 to 113,185,508, reverse strand). Ensembl gene ENSG00000123064.
Subcellular location: Nucleus, nucleolus; Nucleus, nucleoplasm
Subcellular location (Human Protein Atlas): Golgi apparatus; Nucleoli; Nucleoplasm
Gene Ontology:
Molecular function: nuclear estrogen receptor binding; RNA binding; RNA helicase activity; signaling receptor binding; transcription corepressor activity; ATP binding; ATP hydrolysis activity; nucleic acid binding
Biological process: RNA metabolic process; RNA processing; estrogen receptor signaling pathway; rRNA processing; negative regulation of DNA-templated transcription
Cellular component: membrane; nucleolus; nucleus; nucleoplasm
Genetic constraint (gnomAD): Loss-of-function variants: 67 observed, 100.05 expected, observed/expected ratio (o/e) 0.67, 90% interval 0.55 to 0.82. The upper end of that interval is the gene's LOEUF score, 0.82, which puts it in group 3 of 6, group 1 being the genes least tolerant of losing a copy. Missense variants: 1,206 observed, 1,209.1 expected, observed/expected ratio (o/e) 1, 90% interval 0.95 to 1.05. Synonymous variants: 514 observed, 502.69 expected, observed/expected ratio (o/e) 1.02, 90% interval 0.95 to 1.1.
Homologues: Orthologues: chimpanzee DDX54 (99% identical), macaque DDX54 (97% identical), pig DDX54 (89% identical), dog DDX54 (88% identical), guinea pig DDX54 (88% identical), mouse Ddx54 (85% identical), rat Iqcd (83% identical), tropical clawed frog ddx54 (62% identical), zebrafish ddx54 (60% identical), Caenorhabditis elegans Y94H6A.5 (38% identical), Drosophila melanogaster CG32344 (37% identical). Paralogues in human: DDX27 (20% identical), DDX46 (19% identical), DDX42 (19% identical), DDX18 (19% identical), DDX49 (18% identical), DDX3X (18% identical), DDX50 (18% identical), DDX21 (17% identical), DDX3Y (17% identical), DDX10 (17% identical), DDX17 (17% identical), DDX24 (17% identical), and 26 more.
Diseases named in the same sentence as DDX54 in open-access papers:
DDX54 is named in the same sentence as 12 diseases in open-access papers, as found by Europe PMC text mining. Sharing a sentence is not in itself a finding about the gene and the disease. The quoted sentences say what the papers report.
breast carcinoma (2 papers, 2021 to 2025). "Nucleoplasm relocation of DDX54 is also seen in human breast carcinoma cells exposed to ionizing radiation (IR); however, this relocation enables DDX54 to facilitate alternative splicing of IR-induced pre-mRNAs." (PMID 40793791, 2025). "For example, DDX54 knockdown radiosensitizes breast cancer cells likely due to the role of DDX54 in regulating gene expression upon irradiation." (PMID 34680866, 2021).
osteosarcoma (2 papers, 2022 to 2025). A usually aggressive malignant bone-forming mesenchymal neoplasm, predominantly affecting adolescents and young adults. "According to another study that used qRT-PCR and western blot techniques, CBR3-AS1 modifies the miR-140-5p/DDX54-NUCKS1-mTOR signaling pathway network, hence potentially contributing to an oncogenic function in osteosarcoma." (PMID 40356687, 2025). "For instance, lncRNA CBR3-AS1 targeted the network of miR-140-5p-DDX54-NUCKS1-mTOR signaling pathway and contributed to osteosarcoma progression." (PMID 35992869, 2022).
triple-negative breast carcinoma (2 papers, 2021 to 2023). An invasive breast carcinoma which is negative for expression of estrogen receptor (ER), progesterone receptor (PR), and human epidermal growth factor receptor 2 (HER2). "In triple-negative breast cancer, PITPNA-AS1 upregulates SIK2 to exert oncogenic function through miR-520d-5p and DDX54." (PMID 38100482, 2023).
colon cancers (1 paper, 2021). "Of which, DDX54 is confirmed to be highly expressed in CRC tumor tissues, which implied a closely association of DDX54 with colon cancers." (PMID 33968751, 2021). "The DDX54 expression was also detected in colorectal cancer cell lines and the results showed that DDX54 was significantly overexpressed in colon cancer cell lines compared to t he normal cell line NCM-460." (PMID 33968751, 2021). "Here, we found DDX54 was overexpressed in CRC tissues by the label-free mass spectrum, which was also verified in tissue microarray of colon cancer, as well as the CRC cell lines and TCGA database." (PMID 33968751, 2021). "Moreover, to further determine the expression status of DDX54 in CRC patients, immunohistochemistry staining was performed with tissue microarray containing 96 colon cancer tissues and 66 normal tissues." (PMID 33968751, 2021).
colorectal cancer (1 paper, 2021). A primary or metastatic malignant neoplasm that affects the colon or rectum. "Association between DDX54 expression and clinicopathological features of patients with colorectal cancer." (PMID 33968751, 2021). "The DDX RNA helicase family members have been found to play a role in various cancers; however, the role of DDX54 in colorectal cancer is still unclear and needed to be defined." (PMID 33968751, 2021).
gastric tumors (1 paper, 2023). "For instance, SNHG10 promotes the growth and migration of gastric tumors by targeting the miR-495-3p/CTNNB1 axis, activating the WNT pathway and the DDX54-mediated PBX3 feedback pathway." (PMID 36871072, 2023).
Lymphadenopathy (1 paper, 2025). Enlargement (swelling) of a lymph node. "A nomogram based on the most predictive clinical variables (age, Tis (in situ), gender, history of NMIBC, and lymphadenopathy) and genes selected following the Akaike information criterion (AIC) (CBTB16, CHMP6, DDX54, CASP8, LOR, and PLEC) was then created." (PMID 40149716, 2025).
cancer (4 papers, 2021 to 2025). A tumor composed of atypical neoplastic, often pleomorphic cells that invade other tissues. "DEAD-box helicase 54 (DDX54) was recognized as a member of RBPs and reported as an oncogene in some cancers." (PMID 34353336, 2021). "circHIPK3 contains multiple sites for the same RBPs (e.g., DDX54, EIF4A3, FMR1, IGF2BP1, IGF2BP2, LIN28B and MOV10), many of which are involved in chemoresistance and organelle-like structures, such as Cajal body and P-body which are associated with cancer." (PMID 40061896, 2025).
tumor (3 papers, 2021 to 2023). "The mBc1 cluster expressed the pre-B cell receptor-associated molecule VPREB3, the B cell activation marker CD83, and genes associated with cell metabolism, cellular growth, and tumor progression (DDX54, PRDX6, GRHPR)." (PMID 36153593, 2022). "High DDX54 expression was significantly associated with tumor stage and distant metastasis." (PMID 33968751, 2021). "DDX54 was overexpressed in CRC tissues, and high level of DDX54 was associated with tumor stage and distant metastasis as well as shorter overall survival in patients with CRC." (PMID 38023215, 2023). "High DDX54 level was correlated with tumor stage and distant metastasis, which always indicated a poor prognosis to the CRC patients." (PMID 33968751, 2021). "DDX54 knockdown significantly inhibited tumor growth in subcutaneously injected nude mice." (PMID 38023215, 2023). "We found DDX54 was highly expressed in CRC tumor tissues compared to normal tissues." (PMID 33968751, 2021).
DDX54 also shares sentences with these, for which no sentence is quoted: viral infection (2 papers); neuroblastoma (1); Pan (1).